SNORD111B (small nucleolar RNA, C/D box 111B)
Synonyms: hsa-mir-3647; formerly MIR3647
Gene: Small nucleolar RNA gene on chromosome 16 (70,529,509 to 70,529,588, forward strand). Ensembl gene ENSG00000221514.
Gene Ontology:
Biological process: RNA processing
Cellular component: nucleolus
Homologues: Orthologues: chimpanzee SNORD111B (100% identical), guinea pig SNORD111B (94% identical), macaque SNORD111B (94% identical), pig SNORD111B (92% identical), rabbit SNORD111B (91% identical), rat Snord111b (86% identical), mouse Gm22193 (85% identical). Paralogues in human: SNORD111 (78% identical).